MPP7 (MAGUK p55 scaffold protein 7)
Description:
Acts as an important adapter that promotes epithelial cell polarity and tight junction formation via its interaction with DLG1. Involved in the assembly of protein complexes at sites of cell-cell contact.
Synonyms: FLJ32798
Tractability: Antibody: UniProt places it where antibodies can reach, with high confidence; its Gene Ontology location is reachable by antibodies, with medium confidence. PROTAC: ubiquitination databases record sites on it; its protein half-life has been measured.
Gene: Protein-coding gene on chromosome 10 (28,050,993 to 28,335,290, reverse strand). Ensembl gene ENSG00000150054.
Subcellular location: Membrane; Lateral cell membrane; Cell junction, tight junction; Cell junction, adherens junction; Cytoplasm, cell cortex; Cytoplasm
Subcellular location (Human Protein Atlas): Cell Junctions; Nucleoplasm
Pathways (Reactome):
Signal Transduction: RAC1 GTPase cycle; RAC2 GTPase cycle; RAC3 GTPase cycle; RHOG GTPase cycle; RHOJ GTPase cycle; RHOQ GTPase cycle
Gene Ontology:
Molecular function: cadherin binding; molecular adaptor activity; protein binding; protein domain specific binding; signaling adaptor activity
Biological process: bicellular tight junction assembly; positive regulation of protein-containing complex assembly; protein localization to adherens junction; establishment of cell polarity
Cellular component: adherens junction; bicellular tight junction; cell junction; cytoplasm; MPP7-DLG1-LIN7 complex; cell-cell junction; plasma membrane; cell cortex; lateral plasma membrane; membrane
Genetic constraint (gnomAD): Loss-of-function variants: 40 observed, 53.74 expected, observed/expected ratio (o/e) 0.74, 90% interval 0.58 to 0.97. The upper end of that interval is the gene's LOEUF score, 0.97, which puts it in group 4 of 6, group 1 being the genes least tolerant of losing a copy. Missense variants: 437 observed, 509.23 expected, observed/expected ratio (o/e) 0.86, 90% interval 0.79 to 0.93. Synonymous variants: 187 observed, 187.22 expected, observed/expected ratio (o/e) 1, 90% interval 0.89 to 1.13.
Homologues: Orthologues: chimpanzee MPP7 (99% identical), macaque MPP7 (99% identical), dog MPP7 (97% identical), guinea pig MPP7 (96% identical), rat Mpp7 (95% identical), pig MPP7 (94% identical), rabbit MPP7 (94% identical), mouse Mpp7 (93% identical), tropical clawed frog mpp7 (83% identical), zebrafish mpp7a (76% identical), Drosophila melanogaster metro (41% identical), Caenorhabditis elegans magu-1 (35% identical), and 2 more. Paralogues in human: MPP3 (56% identical), MPP4 (42% identical), PALS1 (38% identical), MPP2 (37% identical), PALS2 (35% identical), CASK (32% identical), MPP1 (27% identical).
Diseases named in the same sentence as MPP7 in open-access papers:
MPP7 is named in the same sentence as 45 diseases in open-access papers, as found by Europe PMC text mining. Sharing a sentence is not in itself a finding about the gene and the disease. The quoted sentences say what the papers report.
pancreatic ductal adenocarcinoma (3 papers, 2020 to 2024). An infiltrating adenocarcinoma that arises from the epithelial cells of the pancreas. "Furthermore, MPP7 has been implicated in the regulation of autophagy in pancreatic ductal adenocarcinoma (PDAC)." (PMID 39224268, 2024). "In addition, New M et.al demonstrated that MPP7 is novel regulators of autophagy, which was thought to be responsible for the prognosis of pancreatic ductal adenocarcinoma." (PMID 32854645, 2020).
esophageal cancer (2 papers, 2022 to 2024). A primary or metastatic malignant neoplasm involving the esophagus. "Transcriptome sequencing after MPP7 knockdown in esophageal carcinoma cells showed that wound-healing-associated proteins were down-regulated, and the TGF-β pathway was one of the important signaling pathways." (PMID 36143417, 2022). "Expression analyses of immunohistochemical microarrays with survival and prognostic information of 103 patients with esophageal cancer demonstrated that MPP7 was overexpressed in 52 patients, who showed poor survival rates." (PMID 36143417, 2022). "The transcriptional expression of MPP7 in esophageal cancer in TCGA database increased successively from normal epithelial, to esophageal adenocarcinoma, to esophageal squamous cell carcinoma." (PMID 36143417, 2022). "In this study, we investigated the expression profile of MPP7 and its functional impact on esophagus cancer." (PMID 36143417, 2022). "We confirmed that MPP7 knockdown in esophageal cancer cell line KYSE-150 significantly reduced cell migration and invasion." (PMID 36143417, 2022). "Transcriptome sequencing further clarified the specific mechanism and signaling pathway of MPP7 in esophageal cancer." (PMID 36143417, 2022). "In this study, we investigated the expression of MPP7 and its functional impact on esophageal cancer for the first time." (PMID 36143417, 2022). "The transcriptional expression of MPP7 in esophageal cancer in TCGA database increased successively from normal epithelial cells, to esophageal adenocarcinoma, to esophageal squamous cell carcinoma." (PMID 36143417, 2022). "This means that esophageal cancer cells with MPP7 knockdown had a decreased ability to metastasize in nude mice (p = 0.0006)." (PMID 36143417, 2022). "MPP7 plays an important role in regulating cell polarity, and esophageal cancer has the abilities to easily invade basement membrane and to perform distant lymph-node metastasis." (PMID 36143417, 2022). "We used siRNA MPP7-472 to inhibit the expression of MPP7 in esophageal cancer cells KYSE-150, followed by transcriptome sequencing." (PMID 36143417, 2022). "MPP7 knockdown in esophageal carcinoma cells with transcriptome sequencing showed that wound-healing-associated proteins were down-regulated, and the TGF-beta pathway was one of the important signaling pathways." (PMID 36143417, 2022). "MPP7 has been characterized as a biomarker for esophageal cancer." (PMID 39224268, 2024). "Notably, immunohistochemical results demonstrated that high levels of MPP7 were related to poor prognosis in patients with esophageal cancer." (PMID 39224268, 2024). "Western blot assays verified that the signaling pathway of MPP7 affecting esophageal cancer cells could be the TGF-beta pathway, which was consistent with the results of transcriptomic sequencing." (PMID 36143417, 2022). "Based on the close relationship between esophageal squamous epithelial cells and cell polarity, we speculated that MPP7 plays an important role in the pathogenesis of esophageal cancer, so we conducted the studies here described." (PMID 36143417, 2022). "In summary, our results indicated that MPP7 could have an oncogenic role in human esophagus cancer, thus demonstrating its potential as a novel biomarker for the diagnosis and/or treatment of esophagus cancer." (PMID 36143417, 2022). "Herein, our results indicated that MPP7 could have an oncogenic role in human esophagus cancer, thus demonstrating its potential as a novel biomarker for the diagnosis and/or treatment of esophagus cancer." (PMID 36143417, 2022). "In our study, including in vivo and in vitro analyses, MPP7 knockdown could reduce the migration and invasion abilities of esophageal cancer." (PMID 36143417, 2022). "In conclusion, MPP7 was highly expressed in esophageal carcinoma and could regulate the migration and invasion of esophageal squamous cell carcinoma by affecting cell polarity and the TGF-β signaling pathway." (PMID 36143417, 2022).
esophageal cancer (continued). "Therefore, MPP7 has the potential to be a target gene in the treatment of esophageal cancer." (PMID 36143417, 2022). "Immunohistochemistry showed that MPP7 was overexpressed in esophagus cancer tissues and was negative in normal tissue (p = 0.02)." (PMID 36143417, 2022). "Therefore, we analyzed and identified MAGUK p55 scaffold protein 7 (MPP7), which is highly expressed in esophageal cancer patients, leading to poor survival rates, using immunohistochemical microarray and bioinformatics." (PMID 36143417, 2022). "However, to date, the expression of MPP7 and its potential functional impact on esophageal cancer have not been investigated and remain elusive." (PMID 36143417, 2022). "However, since most esophageal cancers in China are cell squamous cell carcinoma, we were not able to obtain the expression and clinical significance of MPP7 in esophageal adenocarcinoma, and relevant data are expected to be further supplemented in the future." (PMID 36143417, 2022).
lung adenocarcinoma (2 papers, 2022 to 2024). A carcinoma that arises from the lung and is characterized by the presence of malignant glandular epithelial cells. "Phosphorylated MPP7 expression was specific to breast cancer, lung adenocarcinoma, HNSC, and ccRCC." (PMID 39224268, 2024).
open-angle glaucoma (2 papers, 2016 to 2022). Chronic outflow obstruction of the eye's drainage canals that can lead to increased internal eye pressure and optic nerve damage. "MPP7 is a novel candidate gene for primary open-angle glaucoma (POAG), and there is evidence that its expression in relevant eye tissues and its dysregulation under mechanical stress may mimic disease scenarios." (PMID 36143417, 2022).
osteoporosis (2 papers, 2016 to 2025). A condition of reduced bone mass, with decreased cortical thickness and a decrease in the number and size of the trabeculae of cancellous bone (but normal chemical composition), resulting in increased fracture incidence. "Reports suggest that MPP7 is a susceptibility gene for site-specific bone mineral density and osteoporosis." (PMID 27001270, 2016). "Collectively, our findings, together with zebrafish genetic evidence, indicate that MPP7 plays a critical role in osteoblast differentiation and mineralization and may contribute to osteoporosis susceptibility in humans." (PMID 41105261, 2025).
ovarian carcinoma (2 papers, 2024). A malignant neoplasm originating from the surface ovarian epithelium. "In this study, we investigated the expression profile of MPP7 and its functional role in epithelial ovarian cancer." (PMID 39006077, 2024). "The CPTAC data showed that MPP7 total protein expression in primary ovarian cancer, clear cell RCC (ccRCC), colon cancer, GBM, HNSC, UCEC, pancreatic adenocarcinoma (PAAD), and hepatocellular carcinoma (HCC) was significantly lower compared to healthy tissues (P < 0.001)." (PMID 39224268, 2024). "Through analysis of TCGA and GEO databases, combined with immunohistochemical staining of ovarian tumor tissue chips, it was found that MPP7 is significantly overexpressed in epithelial ovarian cancer tissue, and its high expression is closely related to poor prognosis of patients." (PMID 39006077, 2024). "MAGUK P55 scaffold protein 7 (MPP7) plays an important role in the establishment of epithelial cell polarity, but its potential significance in epithelial ovarian cancer is still unclear." (PMID 39006077, 2024).
acute myeloid leukemia (1 paper, 2024). Acute myeloid leukemia (AML) is a group of neoplasms arising from precursor cells committed to the myeloid cell-line differentiation. "We analyzed the differential MPP7 expression in uterine carcinosarcoma (UCS), testicular germ cell tumors (TGCT), brain lower-grade glioma (LGG), acute myeloid leukemia (AML), and compared them with healthy tissues in the GTEx dataset for reference (P < 0.05)." (PMID 39224268, 2024).
breast carcinoma (1 paper, 2024). "We discovered a statistical association between poor OS and high MPP7 expression in patients with breast cancer using the GEPIA2 tool (P = 0.01)." (PMID 39224268, 2024). "In breast cancer, ectopic expression of MPP7 promotes cell migration and invasion by modulating epithelial–mesenchymal transition and activating the epidermal growth factor receptor signaling." (PMID 39224268, 2024). "MPP7 promotes breast cancer aggressiveness via epidermal growth factor receptor signaling." (PMID 39224268, 2024).
esophageal adenocarcinoma (1 paper, 2022). A malignant tumor with glandular differentiation arising predominantly from Barrett mucosa in the lower third of the esophagus. "TCGA database showed that the transcriptional expression level of MPP7 increased successively from normal epithelium, to esophageal adenocarcinoma epithelium, to esophageal squamous cell carcinoma (p = 0.03)." (PMID 36143417, 2022). "TCGA data also showed that the transcription level of MPP7 increased gradually from normal epithelium, to esophageal adenocarcinoma, to esophageal squamous cell carcinoma." (PMID 36143417, 2022).
esophageal squamous cell carcinoma (1 paper, 2022). Esophageal squamous cell carcinoma (ESCC) is a type of esophageal carcinoma (EC) that can affect any part of the esophagus, but is usually located in the upper or middle third. "MPP7 is expected to become a new therapeutic target and prognostic marker of esophageal squamous cell carcinoma." (PMID 36143417, 2022).
heart malformations (1 paper, 2021). "Furthermore, in two non-consanguineous unrelated individuals with heart malformations, among other disorders, microdeletions at 10p11.23-p12.1 (overlapping ARMC4, MPP7, BAMBI and WAC) were identified." (PMID 34324492, 2021).
Hodgkins lymphoma (1 paper, 2024). A heterogeneous group of malignant lymphoid neoplasms of B-cell origin characterized histologically by the presence of Hodgkin and Reed-Sternberg (HRS) cells in the vast majority of cases. "Notably, MPP7 expression may be associated with different tumors, including AML, Hodgkin lymphoma, and leiomyosarcoma." (PMID 39224268, 2024).
Intellectual disability (1 paper, 2016). "MPP7 has also been implicated in intellectual disability and/or multiple congenital anomalies (ID/MCA) through identification of single gene de novo copy number variations." (PMID 27001270, 2016).
left ventricular hypertrophy (1 paper, 2014). Enlargement of the LEFT VENTRICLE of the heart. "Finally, Mpp7, which has been determined to cause at least one case of Maturity-onset diabetes of the young (MODY) and has been associated with left ventricular hypertrophy, BMI and incidence of cardiovascular diseases in the Framingham study." (PMID 24628878, 2014).
leukemia (1 paper, 2025). A malignant (clonal) hematologic disorder, involving hematopoietic stem cells and characterized by the presence of primitive or atypical myeloid or lymphoid cells in the bone marrow and the blood. "Finally, public RNA-seq data from 93 leukemia cell lines for the identified NKX6-3 target genes show reduced activity of CD109 and overexpression of GP5 and MPP7 in RCH-ACV and MHH-CALL-3, highlighting the suitability of these cell lines as models for their investigation in follow-up studies." (PMID 41153416, 2025).
osteosarcoma (1 paper, 2025). A usually aggressive malignant bone-forming mesenchymal neoplasm, predominantly affecting adolescents and young adults. "To further confirm the role of MPP7 in osteogenic differentiation and mineralization, we generated a CRISPR/Cas9-mediated MPP7 KO in the human osteosarcoma HOS and MG-63 cell lines and assessed their osteogenic potential in vitro." (PMID 41105261, 2025). "To confirm its direct involvement in bone metabolism, we examined the role of MPP7 in bone mineralization and OP by analyzing its expression in human bone and muscle tissues and by generating a CRISPR/Cas9-mediated MPP7 KO in a human osteosarcoma cell model of osteogenesis." (PMID 41105261, 2025). "Furthermore, using CRISPR/Cas9-mediated MPP7 knockout (KO) in the human osteosarcoma HOS cell line, we demonstrate that MPP7 is critical for mineralization via regulation of ALPL expression." (PMID 41105261, 2025). "Furthermore, we generated a CRISPR/Cas9-mediated MPP7 knockout in the human osteosarcoma HOS cell line and demonstrated that MPP7 deletion impairs osteogenic differentiation and completely abrogates mineralization through downregulation of ALPL expression." (PMID 41105261, 2025).
prostate adenocarcinoma (1 paper, 2024). "DFS evaluation indicated that high MPP7 expression was associated with poor prognosis in ACC (P = 0.015), KIRP (P = 0.0039), LGG (P = 0.0028), prostate adenocarcinoma (PRAD) (P = 0.0075)." (PMID 39224268, 2024).
retinal disease (1 paper, 2014). "BBS9, MPP7, MED27, these three genes found here to interact with CFH have also been reported to be important for retinal disease." (PMID 24901472, 2014).
rhabdomyosarcoma (1 paper, 2024). A rare aggressive malignant mesenchymal neoplasm arising from skeletal muscle. "Whether Mpp7 and Amot also contribute to cancers originating from MuSCs, e.g., rhabdomyosarcoma, deserves future attention." (PMID 39496834, 2024).
scrapie (1 paper, 2012). A fatal disease of the nervous system in sheep and goats, characterized by pruritus, debility, and locomotor incoordination. "We report here for the first time the upregulation of the gene encoding the MPP7 protein in preclinical scrapie and its positive association with PrPSc deposition, suggesting a possible alteration of cell-cell adhesion the early stages of the disease." (PMID 22897917, 2012).
skin cutaneous melanoma (1 paper, 2024). "Patients with skin cutaneous melanoma (SKCM) exhibited the highest prevalence of MPP7 alterations (>11 %)." (PMID 39224268, 2024).
stomach adenocarcinoma (1 paper, 2024). "Moreover, HEPIA2's "Pathological Stage Plot" module was used to determine whether there is a relationship between MPP7 expression and cancer pathological stage, for example, BRCA, KIRC, stomach adenocarcinoma (STAD) (P < 0.05)." (PMID 39224268, 2024).
uveal melanoma (1 paper, 2024). A melanoma derived from melanocytes of the uveal tract. "Our analysis revealed a statistically significant positive relationship between the immunological infiltration of CD8+ T cells and MPP7 expression in PAAD, STAD, and uveal melanoma, as confirmed by most available algorithms." (PMID 39224268, 2024).